HOTAIR (HOX transcript antisense RNA)
Diseases named in the same sentence as HOTAIR in open-access papers (continued):
Sharing a sentence is not in itself a finding about the gene and the disease.
tumor (continued). "Finally, we sought to identify the role of serum-EVs containing HOTAIR in tumor resistance to TMZ by regulating the miR-526b-3p/EVA1 axis in vivo." (PMID 35418162, 2022). "HOTAIR can regulate multiple tumor-related cell pathways through PRC2-regulated miRNA pathways." (PMID 35093153, 2022). "The upregulation of tumour tissue-derived lncRNAs (HOTAIR, MALAT1, SHNG1 and SHNG6) might be adverse prognostic factors of GC." (PMID 36310592, 2022). "Interestingly, all tumor samples from cardia were HOTAIR positive, whereas in GC tumors from the corpus, the HOTAIR expression was found only in 53.3% (P = 0.016)." (PMID 35347094, 2022). "Although HOTAIR acts as a tumor oncogene and its overexpression has been indicated in the primary and metastatic GC compared to adjacent non-tumor tissues, still it is regarded as an independent diagnosis biomarker to predict the risk GC and mortality rates in patients with GC." (PMID 35186192, 2022). "Moreover, HOTAIR depletion significantly suppressed xenograft tumor growth as examined by tumor volume for 4 months." (PMID 36273585, 2022). "HOTAIR can also influence the drug resistance of HCC cells to anti-tumor drugs by regulating miRNA." (PMID 35093153, 2022). "HOTAIR also performs its oncogenic role by acting as a decoy for tumor-suppressor miR-193a." (PMID 36362925, 2022). "Additionally, LncRNA HOTAIR is positively related to tumor recurrence and epithelial to mesenchymal transition (EMT)." (PMID 34221014, 2021). "Furthermore, HOTAIR is able to promote tumor invasiveness and progression in ESCC cells by acting as a miR-130a-5p sponge." (PMID 33540611, 2021). "Furthermore, the study determined that the high level of lncRNA HOTAIR was related to hepatocarcinogenesis and metastasis, and overexpression of lncRNA HOTAIR is also a predictor of tumor recurrence in HCC." (PMID 34130594, 2021). "Additionally, HOTAIR knockdown inhibits tumor growth and HOTAIR overexpression accelerates tumorigenicity and lung metastasis in mouse models of RCC." (PMID 33593347, 2021). "Knockdown of HOTAIR in PC cells suppressed the expression levels of miR-613 and tumor growth, suggesting that the oncogenic role of HOTAIR might be correlated with miR-613." (PMID 34760707, 2021). "In ACC, HOTAIR is overexpressed in tumor tissues compared with normal tissues." (PMID 33746977, 2021). "Similarly, HOTAIR upregulation in DLBCL tumor tissues was correlated with clinical stage, B symptoms, IPI scores and tumor volumes, and predicted poor prognosis and poor survival rates in DLBCL patients." (PMID 33483590, 2021). "Additionally, HOTAIR promoted tumor proliferation by acting as a ceRNA for miR-218, resulting in upregulation of PDE7A." (PMID 34322395, 2021). "The role of HOTAIR in soft tissue sarcomas is mainly related to specific tumor types." (PMID 34576322, 2021). "Furthermore, HOTAIR promotes tumor progression through activation of β-catenin, PKM2, and other pathways." (PMID 34887871, 2021). "In BC, overexpressed HOTAIR plays a crucial role in tumor progression by directly or indirectly modulating several molecular pathways involved in growth, malignant proliferation, invasion, self-renewal, EMT, metastatic spread, and poor prognosis, including drug resistance." (PMID 34885213, 2021). "In epithelial OC, overexpression of HOTAIR predicts elevated tumor metastasis and poor prognosis." (PMID 34885213, 2021). "The induction of HOTAIR expression can often be mediated by the tumor microenvironment (TME)." (PMID 33540611, 2021). "HOTAIR participates in cell growth and promotes tumor development and metastasis." (PMID 33747903, 2021). "Moreover, the high expression of HOTAIR was related to the proliferation, invasion, and metastasis of tumor cells as well as the poor prognosis." (PMID 33473276, 2021). "Higher expression of HOTAIR was related to tumor size and TNM stage." (PMID 33954114, 2021).
tumor (continued). "In five fresh PCa surgical specimens and the corresponding adjacent normal tissues, the HOTAIR mRNA and H3K27me3 protein levels were significantly higher in the tumour tissues (T) than in the adjacent normal tissues (N), while the mRNA and protein levels of hepaCAM showed the opposite pattern." (PMID 33024272, 2021). "AQB treatment resulted in a significant reduction of the intracranial tumor volume compared with the DMSO group(43% reduction with P < 0.05), contrarily, overexpression of HOTAIR increased the malignant progression of the tumor (52% enhancement in nude mice, P < 0.05)." (PMID 34887871, 2021). "Furthermore, one study analyzed the expression of lncRNA HOTAIR in five pediatric tumor types and found higher expression of this gene in juvenile PAs." (PMID 34552822, 2021). "HOTAIR has been reported to promote tumor cell invasion and metastasis by regulating the EMT." (PMID 32462038, 2020). "HOTAIR is the first lncRNA found to be able to promote tumor progression." (PMID 32929060, 2020). "In bladder cancer patients, HOTAIR is an independent prognostic factor of tumor recurrence." (PMID 32397382, 2020). "Here, we summarize ncRNAs with tumor-promoting functions: HOTAIR, HOTTIP, MALAT1, lncRNA H19, lncRNA PVT1, circ-RNA ciRS-7, circ-0030235, circ-RNA_100782, circ-LDLRAD3, circ-0007534, circRHOT1, circZMYM2, circ-IARS, circ-RNA PDE8A, miR-21, miR-155, miR-221/222, miR-196b, miR-10a." (PMID 32257946, 2020). "In addition to the indicated tumour suppressor genes, it has been determined that HOTAIR can mediate interaction of EZH2 with the specific region of PTEN." (PMID 32245498, 2020). "Amounting evidence suggests that HOTAIR plays a tumor promoting role in CRPC stage." (PMID 32657763, 2020). "HOTAIR also exerts its tumor-promoting effect by sponging miR-17-5p; therefore, the HOTAIR/miR-17-5p axis could also be a promising therapeutic target for future treatment of CC." (PMID 33371204, 2020). "Further mechanistic study also demonstrated that propofol could exert its anti‐tumor activity through inhibition of HOTAIR expression." (PMID 31953926, 2020). "Lots of scientific researches have confirmed that HOTAIR is over-expressed in a variety of solid tumors, and the abnormal increase of HOTAIR is closely related to the infinite proliferation of tumor cells, growth promotion, angiogenesis, migration and metastasis." (PMID 32700738, 2020). "Moreover, the shRNA-mediated knockdown of HOTAIR in gastric cancer cells decreased the tumor formation and metastatic potential in nude mice." (PMID 32575858, 2020). "In addition, in vivo experiments demonstrated that HOTAIR knockdown potentiated IR-mediated anti-tumor effects by increasing miR-93 and cleaved caspase 3 expression, and reducing ATG12 and LC3 II expression in CRC xenograft tumors." (PMID 32144238, 2020). "Moreover, there was an obvious relationship between high expression of HOTAIR and clinicopathological parameters, such as venous invasion, advanced tumor infiltration and distant metastasis." (PMID 32104724, 2020). "Moreover, HOTAIR loss enhanced radiosensitivity through regulating miR-93/ATG12 axis in CRC cells and CRC xenograft tumor models." (PMID 32144238, 2020). "Knockdown of HOTAIR increased the inhibitory effect of DDP on tumor growth in vivo." (PMID 32349783, 2020). "In NPC tumor tissues, HOTAIR overexpression promotes angiogenesis and tumor growth by directly activating the transcription of vascular endothelial growth factor-A (VEGF-A) and glucose-regulated protein 78 (GRP78) as well as through GRP78-mediated upregulation of VEGFA and Ang2 expression." (PMID 31336999, 2019). "Years ago, it was speculated that HOTAIR might promote tumor aggressiveness through the upregulation of vascular endothelial growth factor (VEGF) and matrix metalloproteinase (MMP) and EMT-related genes." (PMID 31744046, 2019). "Targeting HOTAIR could induce apoptosis and inhibit tumor growth in HNSCC both in vitro and in vivo." (PMID 31032351, 2019).
tumor (continued). "In addition, higher HOTAIR expression was correlated with tumor differentiation, lymph node and distant metastasis, and clinical stage." (PMID 31281803, 2019). "In addition, HOTAIR knockdown significantly suppresses tumor growth and ki-67 expression, increases miR-217 levels and decreases the expression of HIF-1α and AXL, inhibiting tumor growth and EMT." (PMID 31072041, 2019). "Besides, silenced HOTAIR or overexpressed miR‐206 repressed the tumour growth of nude mice with HNSCC." (PMID 31297902, 2019). "We found that the tumor cell lines with high levels of HOTAIR and EZH2 were sensitive to AQB." (PMID 31367244, 2019). "AQB exhibited potent anti-tumor activity in the cells expressing high levels of HOTAIR and EZH2." (PMID 31367244, 2019). "The elucidation of the role of MKL1 may shed light into the molecular basis of the HOTAIR induced tumor metastasis." (PMID 29391067, 2018). "HOTAIR overexpression correlates with more severe tumour distant metastases and poorer prognosis." (PMID 28941134, 2018). "Collectively, these data suggest that HOTAIR could inhibit tumor suppressive miRNAs through a combination of multiple mechanisms to amplify its oncogenic effects." (PMID 29702599, 2018). "Also, the expression level of HOTAIR has been found significantly increased in HNC tissues than in paired adjacent non-tumor tissues." (PMID 29416703, 2018). "Moreover, in our study Bax was upregulated after knockdown of HOTAIR, on the other hand, Bcl-2 with low expression levels, this is probably an indirect argument that HOTAIR promotes tumor development and progression in CCA36–40." (PMID 30111807, 2018). "HOTAIR overexpression promoted tumor growth in mice bearing HeLa and exposed to radiation." (PMID 30355300, 2018). "Moreover, increased HOTAIR was a prognostic biomarker of tumor recurrence following liver transplantation." (PMID 28810927, 2017). "The clinical significance of HOTAIR has been summarized and discussed in multiple meta-analysis studies, suggesting that the expression of HOATIR is positively associated with an advanced clinical tumor stage, metastasis and worse prognosis." (PMID 29228709, 2017). "High HOTAIR expression is correlated with tumor stage and poor prognosis." (PMID 28182000, 2017). "HOTAIR is abundantly expressed in NPC tumor tissues and promotes tumor angiogenesis and growth." (PMID 27802187, 2017). "Knock-down of HOTAIR in L3.6pl cells suppressed the in vivo tumor growth and also suppressed the expression levels of miR-613, suggesting that the in vivo tumor suppressive role miR-613 may be correlated with HOTAIR." (PMID 28415631, 2017). "Recent works reported the inhibitory effect of HOTAIR on miRNAs functions in different neoplasias." (PMID 29147648, 2017). "Further studies showed that overexpression of HOTAIR could promote tumor sphere formation, which upregulated expression of the tumor stem cell-related biomarkers such as Nanog, Oct3/4, Sox2, c-Myc, β-catenin, and Klf4." (PMID 28978188, 2017). "The results showed that HOTAIR expression significantly correlated with clinical tumor stage (OR = 3.90, 95% CI = 3.02–5.03, P < .001), indicating that the clinical tumor stage was more advanced in patients with high HOTAIR expression compared with patients with low HOTAIR expression." (PMID 28591050, 2017). "However, more studies are required to verify the mechanism of HOTAIR in tumor development and its usage as a prognostic marker." (PMID 28591050, 2017). "HOTAIR expression in OSCC tissues is also correlated with a larger tumor size and advanced clinical stages, suggesting that HOTAIR may be used as a biomarker for diagnosing OSCC." (PMID 27802187, 2017).
tumor (continued). "Furthermore, MVIH and HOTAIR facilitate invasion and metastasis by modulating the tumor microenvironment." (PMID 29168767, 2017). "In summary, our meta-analysis demonstrates that high HOTAIR expression may serve as a potential indicator for advanced clinical tumor stage, lymph node metastasis, poor differentiation, and worse prognosis." (PMID 28591050, 2017). "The functional roles of HOTAIR in tumor biology have been largely studied." (PMID 28207735, 2017). "Furthermore, a follow-up study demonstrated that high levels of HOTAIR positively correlate with tumor relapse and short OS." (PMID 28649178, 2017). "HOTAIR overexpression in gastric cancer tissues led to decreased expression of miR-152 and to upregulation of its target, HLA-G (human leukocyte antigen G), which in turn facilitated tumor escape mechanisms." (PMID 29147648, 2017). "Since HOTAIR seemed to be implicated in tumor progression, we chose the OSCC with low level of HOTAIR, FaDu and OECM-1, to generate stable HOTAIR-overexpressing cells through lentiviral-mediated transduction in order to verify this hypothesis." (PMID 29228709, 2017). "In cervical cancer, HOTAIR promotes tumor growth and invasion by targeting the Notch pathway." (PMID 28931862, 2017). "Thus, it is biologically conceivable that the genetic variants of HOTAIR may affect the activities of certain regulatory factors and further regulate the aberrant expression of HOTAIR, which might be one of the underlying mechanisms that affect tumour susceptibility and prognosis." (PMID 27010768, 2016). "To explore whether HOTAIR can affect tumour growth in vivo, we inoculated SiHa cells as xenografts into nude mice." (PMID 27323817, 2016). "HOTAIR, one of the most commonly high-regulated lncRNAs in tumor cells, could promote the proliferation and inhibit the apoptosis as an oncogenic lncRNA." (PMID 27660759, 2016). "However, the results indicated that there was a distinct correlation between serum HOTAIR expression and tumour size, LVSI, and LN metastasis." (PMID 27323817, 2016). "High expression of HOTAIR may inhibit the expression of tumour metastasis-suppressor genes, thereby promoting metastasis and malignant transformation." (PMID 27897239, 2016). "On assessing the clinicopathological characteristics of the sample set, survival status was the only characteristic that was significantly associated with HOTAIR expression, i.e., those patients whose tumours were HOTAIR + ve had a poor outcome compared with HOTAIR-ve tumours (P = 0.023)." (PMID 26497652, 2015). "We further show that HOTAIR expression is closely correlated with primary TNBC tumor tissues." (PMID 25883211, 2015). "The inhibition of HOTAIR slowed tumor growth and prolonged survival in a xenograft model." (PMID 25428914, 2015). "HOXC11 expression was well correlated with HOTAIR expression in tumor tissues (r Pearson = 0.96)." (PMID 25994132, 2015). "Multivariate analysis showed that the expression level of HOTAIR was independent of clinical risk factor such as gender, smoking, tumor differentiation and tumor size, but linked with clinical stage and lymphatic metastasis." (PMID 26658322, 2015). "To analyze whether increased HOTAIR expression could define a progression biomarker, we determined the HOTAIR levels in recurrent samples according to the tumor progression." (PMID 26457124, 2015). "LncRNA HOTAIR has a high expression level in metastatic breast cancer tumors, and the inhibition of HOTAIR expression may block tumor metastasis." (PMID 26631459, 2015). "Similarly, increased HOTAIR was shown to be prognostic factor of tumor recurrence following liver transplantation." (PMID 25954300, 2015). "Moreover, the downregulated HOTAIR expression in CD117+CD44+ CSCs significantly decreased the tumor growth and lung metastasis in xenograft mice." (PMID 25792974, 2015). "It has been demonstrated that a novel lncRNA, HOTAIR was involved in various types of tumor." (PMID 24888564, 2014).
tumor (continued). "Further study of HOTAIR-related pathways and the role of HOTAIR in tumorigenesis and tumor progression may identify new treatment targets." (PMID 25334066, 2014). "Examination of the correlation between HOTAIR expression and clinical pathological features showed that HOTAIR upregulation was correlated with larger tumor size, advanced pathological stage, distant metastasis, lymph node metastasis and tumor cell differentiation." (PMID 24775712, 2014). "On the other hand, HOTAIR antagonizes several tumor suppressive miRNAs." (PMID 25491133, 2014). "We observed that knock-down of HOTAIR expression inhibited DU145 cell tumor formation in vivo." (PMID 23936419, 2013). "The expression levels of HOTAIR were upregulated in the tumors of patients with higher tumor burdens; these patients were characterized as having a larger tumor size (P = 0.000), more advanced clinical staging (P = 0.001) and increased lymph node tumor burden (P = 0.029)." (PMID 23717443, 2013). "Following the treatment with cisplatin, the average weight of tumors formed from siRNA/HOTAIR1 or siRNA/control-transfected A549/DDP cells was 204.8±6.8 mg and 423.4±8.4 mg, respectively, and thus, the downregulation of HOTAIR expression led to a 51.8% inhibition of tumor growth (P<0.01)." (PMID 24155936, 2013). "Zhuang and his colleagues showed that tumor-promoting Col-1 up-regulates the expression of HOTAIR in NSCLC cells, suggesting that HOTAIR might play critical roles in lung tumorigenesis." (PMID 24155936, 2013). "HOTAIR, a long intervening non-coding RNA (lincRNA), associates with the Polycomb Repressive Complex 2 (PRC2) and is reported to reprogram chromatin organization and promote tumor progression." (PMID 24155936, 2013). "Although numerous studies have demonstrated the critical functions of HOTAIR in tumor development and metastasis, whether HOTAIR plays an import role during development of chemoresistance in human LADs is still unclear." (PMID 24155936, 2013). "Induction of HOTAIR Expression by Type I Collagen — Because of the tumor-promoting activities of Col-1 and HOTAIR, we sought to determine whether Col-1 regulated the expression of HOTAIR during disruption of acinar morphogenesis of lung epithelial cells." (PMID 23668363, 2013). "HOTAIR expression has recently been reported to be associated with advanced pT stage tumors, and high-expression level has been found to indicate poorer prognosis without any significant association with age, gender, or tumor size." (PMID 39397388, 2025). "Consequently, it is reasonable to suggest that other lncRNAs, such as HOTAIR, may also play a regulatory role in tumor metabolism." (PMID 40072116, 2025). "Moreover, overexpression of HOTAIR leads in several cases to increased cell viability because this lncRNA regulates mechanisms that mediate the proliferation and evasion of apoptosis in tumour cells." (PMID 40072116, 2025). "It is interesting to note that some lncRNAs such as HOTAIR, ANRIL, GAS5, NEAT1, CCAT2, UCA1 are consistently reported to be associated with several prognostic indicators such as advanced FIGO stage, increased tumour growth, lymph node metastasis and lowered survival measures." (PMID 39912983, 2025). "Inhibitors of EZH2 (a component of PRC2) could attenuate the downstream effects of HOTAIR-mediated gene silencing, or lead to the de-repression of tumor-suppressive miRNAs like miR-34a in human pancreatic ductal adenocarcinoma, thereby initiating a cascade of anti-tumor and immunomodulatory effects." (PMID 41221298, 2025). "HOTAIR is closely related to tumors and may be involved in regulating tumor development." (PMID 38277554, 2024). "Therefore, variants in HOTAIR and MIR155HG genes could influence their roles in regulating M1/M2 macrophage balance, as well as immune cell infiltration in the tumor microenvironment and expression of immune checkpoint molecules." (PMID 38339237, 2024).